PAK1 (p21 (RAC1) activated kinase 1)
Diseases named in the same sentence as PAK1 in open-access papers (continued):
Sharing a sentence is not in itself a finding about the gene and the disease.
cardiac hypertrophy (13 papers, 2014 to 2025). "Pak1-deficient mice displayed increased susceptibility to Ang II or isoprenaline mediated cardiac hypertrophy." (PMID 39899001, 2022). "Our findings suggest that Pak1 activation offers a novel therapeutic strategy for management of cardiac hypertrophy and its associated arrhythmias." (PMID 25014109, 2014). "Our data suggest that targeting Pak1 activation represents a novel therapeutic option for the management of cardiac hypertrophy and its associated ventricular arrhythmias." (PMID 25014109, 2014). "PAK1 deficiency leads to cardiac hypertrophy and increased risk of mortality related to heart failure, and PAK1 or PAK2 activation may be beneficial in hypertrophy and heart failure." (PMID 30858169, 2019). "Thus our results suggest that Pak1 activation achieved by specific bioactive peptide represents a potential novel therapeutic strategy for cardiac hypertrophy and associated ventricular arrhythmias." (PMID 25014109, 2014). "Pak proteins are canonical effectors of Rac1 and cardiomyocyte-specific deletion of either Pak1 or Pak2 phenocopies exacerbated cardiac hypertrophy and dysfunction in response to pressure overload or AngII infusion that we observed in Rac1cKI mice." (PMID 40924486, 2025). "We also found Pak1 was present in visceral adipose tissue and observed that its global deletion leads to obesity, cardiac hypertrophy, and diastolic dysfunction specifically in middle‐aged female mice." (PMID 40065530, 2025). "Apart from pressure overload stress-induced cardiac hypertrophy, Pak1 also protects the heart from neuroendocrine agonist-induced hypertrophic stimulation." (PMID 39899001, 2022). "CDC42-knockout and PAK1-knockout mice develop greater cardiac hypertrophy compared with controls, which demonstrates the contradictory roles of CDC42 and PAK1 in cardiac hypertrophy." (PMID 33824277, 2021). "Earlier reports had identified Pak1 as a novel regulator of hypertrophic remodeling whose cardiomyocyte-specific deletion exacerbated cardiac hypertrophy leading to heart failure, following transverse aortic constriction." (PMID 25852566, 2015). "Such cardiac hypertrophy, with improved cardiac function and decreased myocyte apoptosis compared to WT, was reduced in mice over-expressing Pak1, with improved cardiac function and decreased myocyte apoptosis compared to WT." (PMID 25852566, 2015). "In view of these promising results, we proceeded to test whether Pak1 plays a role in cardiac hypertrophy induced by pressure overload and Angiotensin II treatment in a mouse model with cardiac‐specific Pak1 deletion Pak1(cko)." (PMID 40065530, 2025). "Previous reports showed that mice knockout of PAK1 promote isoproterenol-induced cardiac hypertrophy, which could activate Erk1/2 and inhibit protein phosphatase 2A." (PMID 35306484, 2022). "Moreover, cardiomyocyte-specific Pak1 deletion (Pak1-CKO) mice developed significant cardiac hypertrophy accompanied with increased fibrosis and cardiomyocyte size compared to control mice after two weeks of pressure overload stress." (PMID 39899001, 2022). "At the same time, the administration of the ERK1/2 selective inhibitor FR180204 reduced the ERK1/2 phosphorylation and LV myocardial hypertrophy in ISO-treated WT and Pak-1-knockout (KO) mice." (PMID 27941647, 2016). "It has also been reported that through the P21-activated kinase 1 (Pak1)-dependent signaling pathway, BBR (3 mg/kg/d) might suppress the upregulation of Smad3-mediated muscle-specific F-box protein (Fbxo32) in downstream promoter region and take part in the inhibition of myocardial hypertrophy." (PMID 33815112, 2021).
Intellectual disability (12 papers, 2012 to 2025). "Activating mutations in p21-activated kinase 1 (PAK1) cause intellectual disability, neurodevelopmental abnormality, macrocephaly, and white matter anomaly in children." (PMID 40586933, 2025). "Mutations of the auto-inhibitory domain of PAK1 result in constitutive kinase activation in the brains of affected children and cause neurodevelopmental disturbance, macrocephaly, and intellectual disability." (PMID 40586933, 2025). "Our findings align with previous reports of de novo PAK1 variants leading to similar phenotypic presentations, including macrocephaly, seizures, and intellectual disability." (PMID 41516310, 2025). "PAK1 is also implicated in a number of neurodevelopmental and neurodegenerative diseases, including autism, intellectual disability and Alzheimer’s disease." (PMID 26043730, 2015). "Notably, gain-of-function activating mutations in human PAK1 lead to intellectual disability, macrocephaly, and white matter hyperintensity of T2-weighted brain MRI which is indicative of white matter hypomyelination." (PMID 40586933, 2025). "Interestingly, PAK1 mutations also associate with intellectual disability, severe epilepsy, autism spectrum disorder and macrocephaly." (PMID 38454080, 2024). "The introduction of a functional Cr transporter in the CTD-rescue organoids leads to a reduction of GSK3β activation, a restoration of the SOX2 progenitor marker level, as well as of the highlighted proteins linked to intellectual disabilities such as PAK1 and MAP1B." (PMID 37830910, 2023). "In contrast to these reports, the higher PAK1 S199/S204 phosphorylations are relevant to the seizure susceptibility in fragile X mental retardation 1 (Fmr1) KO mice (a Fragile X syndrome model), since FRAX486 (a PAKs inhibitor) reduces audiogenic seizure activity in this model." (PMID 37118736, 2023). "Of interest, this dimerization is inhibited by mutations in PAK3 that lead to mental retardation, suggesting that PAK1 levels may contribute to spine reductions through this mechanism." (PMID 23613712, 2013). "Aberrant activation of PAK1 during neurodevelopment may therefore impair neuronal migration, dendritic spine maturation, and inhibitory/excitatory balance, providing a mechanistic explanation for the convergence of macrocephaly, seizures, and intellectual disability in patients with AID variants." (PMID 41516310, 2025). "Noteworthily, 21 proteins are related to autism spectrum disorders (e.g. PAK2), intellectual disability (e.g. PAK1), neurodevelopmental disorders (e.g. GSK3β) and epileptic encephalopathies (e.g. MAP1B)." (PMID 37830910, 2023). "In our case report, a de novo c.251C > G (p.T84R) variant in PAK1 gene was also identified using WES technology who had similar features including global developmental delay, severe intellectual disability, speech delay, and seizures, without macrocephaly." (PMID 36624491, 2023).
glioblastoma (11 papers, 2019 to 2024). The most malignant astrocytic tumor (WHO grade IV). "Earlier studies identified an association between high PAK1 expression, in general, particularly of phosphorylated cytoplasmic PAK1, and poor prognoses in glioblastoma patients." (PMID 35883575, 2022). "In glioblastoma, PAK1 (p21 activated kinase 1) in the hypoxic environment accelerates the proliferation of tumor cells by mediating autophagy." (PMID 39033180, 2024). "PAK1 promotes cellular proliferation in glioblastoma through regulating the autophagy pathway during hypoxic conditions." (PMID 36830998, 2023). "Glioblastoma: PAK1 is overexpressed in glioblastoma, and its higher expression results in poor prognosis." (PMID 36830998, 2023). "For example, an amphiphilic BCD knockdowns 80% of macropinocytosis gene (PAK1) expression using the BCD/siRNA (1 μM/100 nM) in glioblastoma cells." (PMID 35631507, 2022). "In glioblastoma, PAK1 phosphorylation in the cytoplasm and its expression level correlate with patient prognosis." (PMID 35883575, 2022). "DOCK7 is a RAC-GEF with the potential to regulate F-actin organization, consistent with previous publications reporting DOCK7-mediated RAC1/CDC42 - PAK1 activation in the DNA replication stress response 122, and the promotion of glioblastoma cell invasion by DOCK7 via RAC activation." (PMID 37064875, 2023). "This may be one of the mechanisms by which PAK1 could promote drug resistance in glioblastoma through hypoxia and autophagy signaling." (PMID 36830998, 2023). "Pak1 also plays an instrumental role in initiating hypoxia-induced autophagy and maintaining glioblastoma growth; however, whether Axl/Pak1 signaling plays a role in regulating autophagy remains unknown." (PMID 34074054, 2021). "Upon genotoxic stress induced by irradiation or etoposide treatment in the colon, glioblastoma and PDAC cells activated PAK1 phosphorylates CRAF at Ser338." (PMID 36830998, 2023). "Further, the downregulation of PAK1 mRNA is not easy to integrate when considering that both protein phosphorylation and localization (cytoplasmic versus nuclear) appeared essential for its function and prognosis value in glioblastoma." (PMID 30909495, 2019).
viral infection (11 papers, 2011 to 2025). "Taken together these separate lines of evidence indicate that PAK1 may promote inhibition and/or a deficiency in the immune system caused by virus infection or other conditions." (PMID 28629331, 2017). "Because SARS-CoV-2 induces PAK1 expression in lung cells and PAK1 signaling stimulates as well as represses several cellular genes, a subset of genes in SARS-CoV-2 infected cells might be coinfluenced by a defective vitamin D and viral infection-associated PAK1 upregulation." (PMID 33883570, 2021). "Additionally, another interesting target enzyme to counteract the SARS-CoV-2 viability and progression is the major “pathogenic” kinase PAK1, whose malfunction induces inflammation, viral infection, and immuno-suppression; therefore, PAK1-blockers are considered to have an anti-coronaviral effect." (PMID 34356384, 2021). "Infected cells have been shown to induce the activation of kinases in early events of viral infection, such as the activation of PAK1 upon Myxoma Virus infection." (PMID 25747578, 2015). "Furthermore, propolis block kinase PAK-1, which increases during lung inflammation and fibrosis, and PAK1 inhibitors were reported to rescue the immune system and help resist virus infection." (PMID 35069217, 2021). "This enhancement of virus infection by Pak1 suggests Pak1 might participate in the same pathway that RhoV uses to support the ZIKV lifecycle in host cells." (PMID 34834920, 2021). "Western blottinganalysis revealed significant activation of PAK1 and ROCK in the initial stagesof viral infection.Furthermore, the impact of the PAK inhibitor IPA-3 and the ROCK inhibitorY-27632 on cofilin phosphorylation was examined." (PMID 40094365, 2025). "P21-activated kinase 1 (PAK1) plays a critical role and contributes to various diseases including inflammation, immunosuppression, cancer, viral infection, ageing, and diabetes." (PMID 35873799, 2022). "Inhibitors of the EGFR pathway and the effectors Pak1, Rac1 and PKC reduced viral infection." (PMID 28596575, 2017).
Alzheimer disease (10 papers, 2015 to 2025). A progressive, neurodegenerative disease characterized by loss of function and death of nerve cells in several areas of the brain leading to loss of cognitive function such as memory and language. "In general, Pak1 is implicated in neurodegenerative disorders, such as Alzheimer disease (AD), Huntington disease (HD), and Parkinson disease." (PMID 31201651, 2019). "A study on Alzheimer’s disease found that the activation of the PAK1 signaling pathway can promote the autophagy of microglia, while its inhibitor IPA-3 can lower autophagy." (PMID 35431972, 2022). "PAK3 mutations and PAK1 hyper-activation can cause MR such as X-linked MR (XLMR), Alzheimer disease (AD), and Huntington disease (HD)." (PMID 33796531, 2021). "Recent multiomics studies from Accelerating Medicines Partnership for Alzheimer's Disease and Target Enablement to Accelerate Therapy Development for AD identified p21‐activated kinase 1 (PAK1) as a potential therapeutic target due to its aberrant activation in AD." (PMID 41451871, 2025).
atherosclerosis (10 papers, 2012 to 2025). A disease characterized by the build-up of fatty material and calcium deposition in the arterial wall resulting in partial or complete occlusion of the arterial lumen. "Pak1 expression and activity are increased in atherosclerosis-prone apolipoprotein E-deficient (ApoE-/-) mice." (PMID 39899001, 2022). "Here we report the effect of Pak1 on atherogenesis using atherosclerosis-prone apolipoprotein E-deficient (ApoE−/−) mice as a model." (PMID 26104863, 2015). "Thus, this evidence establishes the PAK1-PPARγ axis as an attractive therapeutic target for the regulation of macrophage polarization implicated in atherosclerosis." (PMID 34603600, 2021). "The study addresses whether PAK1 contributes to inflammatory marker expression in endothelial cells at atherosclerosis-susceptible regions of arteries in vivo." (PMID 22824149, 2012). "Since the inflammatory response plays an important role in vascular diseases like atherosclerosis, aneurysm, etc., understanding PAK1’s role is crucial for managing pathological inflammation and mitigating vascular damage." (PMID 39766303, 2024). "The PAK1 gene also promotes activation of inflammatory pathways in endothelial cells by fluid shear stress, which is the initial stimulator of atherosclerosis." (PMID 36864386, 2023). "Our work provides a promising mechanism and highlights the important role of PAK1 as a promising therapeutic target for atherosclerosis management." (PMID 34603600, 2021). "Collectively, the clearly delineated effect of the “PAK1-PPARγ” axis on macrophage polarization and subsequent foam cell formation indicated the important role of this axis in the development of atherosclerosis." (PMID 34603600, 2021). "Collectively, these findings reveal that PAK1 is an independent effector of macrophage polarization at least partially attributed to regulation of PPARγ expression, which suggested PAK1-PPARγ axis as a novel therapeutic strategy in atherosclerosis management." (PMID 34603600, 2021). "Together, these findings demonstrate that Pak1 plays a crucial role in the pathogenesis of atherosclerosis." (PMID 26104863, 2015). "However, the regulation of NADPH oxidase by Pak1 in the context of inflammation during atherosclerosis is yet to be experimentally verified." (PMID 39899001, 2022). "Similarly, increased Pak1 phosphorylation was also observed in human atherosclerotic arteries, suggesting that Pak1 plays a significant role in the development of atherosclerosis." (PMID 39899001, 2022). "To test this hypothesis, we crossed Pak1 knockout mice to atherosclerosis-prone ApoE−/− mice, to generate ApoE−/−:Pak1−/− mice." (PMID 26104863, 2015). "Therefore, to further define the role of PAK in the biomechanical initiation of the atherosclerotic cascade, we examined inflammatory activation of the endothelium at atherosclerosis-prone sites in PAK-1 knockout mice." (PMID 22824149, 2012). "Therefore, it is reasonable to expect that Nox1/PAK1 may contribute to the initiation and progression of atherosclerosis." (PMID 39721498, 2025). "By using PMs and BMDMs isolated from ApoE knockout mice which were utilized as a classical in vitro model for atherosclerosis, we aimed to investigate the potential role of PAK1 in macrophage activation that may contribute to the development of atherosclerosis." (PMID 34603600, 2021). "In vivo experiments demonstrated that depletion of Pak1 in C57BL/6J mice decreased the expression NF-κB (p65 subunit), implying that Pak1 promotes inflammation at atherosclerosis sites." (PMID 39899001, 2022).
diabetes (10 papers, 2017 to 2025). "Evidence that increased levels of Pak1 activity may be protective provides support for efforts to develop therapeutic approaches activating Pak1 with potential use in prevalent disorders associated with obesity, diabetes, and myocardial dysfunction." (PMID 40065530, 2025). "Because of the increase in vascular L-selectin ligands in some diseases, such as chronic inflammation, acute dermatitis, rheumatoid arthritis, diabetes, and asthma, it would be interesting to test Pak1(T)−/− mice for disease susceptibility in these different conditions." (PMID 30891040, 2019). "These proposed and developing targeted therapeutic strategies, particularly in cardiac dysfunction, cancer, and diabetes/obesity, require consideration and a deep understanding of Pak1 in relation to off‐target effects." (PMID 40065530, 2025). "Literature supporting a role for cDC42 and therefore Pak1 signaling as a critical component of insulin secretion and diseases related to diabetes has been summarized in extensive reviews." (PMID 40065530, 2025). "PAK1 (p21-activated kinase 1) has been known to play a key role in many diseases and disorders including various cancers, neurofibromatosis (NF), type 2 diabetes mellitus, hypertension, pathologic shortened lifespan, and neurodegenerative diseases." (PMID 28098826, 2017). "PAK1 is involved in the second phase of glucose-stimulated insulin secretion and Islets from individuals with T2D have been found deficient in PAK1 protein expression when compared with islets of individuals without diabetes." (PMID 35227251, 2022). "ARPC1B’s effects on diabetes are not limited to immune responses; studies have shown that ARPC1B is a substrate of PAK1 during mitosis, and changes in PAK1 levels regulate the tissue crosstalk of pancreatic β cells, affecting systemic glucose homeostasis." (PMID 40718484, 2025). "Our rationale in presenting this review is to inform those who have not considered Pak1 signaling in thinking about obesity/diabetes/heart disease and to inspire more research into this area of investigation." (PMID 40065530, 2025).
thyroid cancer (10 papers, 2017 to 2025). "Further, PAK1 is important for BRAF-mutated thyroid cancer cell growth and invasion." (PMID 34638434, 2021). "For instance, PAK1 was demonstrated to be a target of miR-7 to participate in regulating the proliferation and metastasis of thyroid cancer cells." (PMID 32190006, 2020). "Hsa-miR-7 plays a role in regulating cell growth, migration, and invasion by targeting PAK1 in thyroid cancer." (PMID 29713312, 2018). "This is particularly true for the RAC1/PAK1 pathway, TWIST1 and EGFR1 proteins, which are known drivers of proliferation and EMT in aggressive thyroid cancer cells." (PMID 34638434, 2021). "Analysis of the biological function of miR-7 in thyroid cancer demonstrated the role of miR-7 in thyroid cell growth and metastasis by targeting cyclin-dependent kinase subunit 2 (CKS2) and p21-activated kinase 1 (PAK1)." (PMID 31835496, 2019). "BRAFV600E has been found to physically interact and activate p21-activated kinase 1 (PAK1), a serine/threonine kinase involved in promoting migration in human thyroid cancer cell lines." (PMID 28350298, 2017). "Among the group I PAKs, siRNA-mediated knockdown of only PAK1 reduced migration significantly in thyroid cancer cell lines, but an additional role for PAK4 was not excluded." (PMID 28178642, 2017).